BCL2 (BCL2 apoptosis regulator)
Diseases named in the same sentence as BCL2 in open-access papers (continued):
Sharing a sentence is not in itself a finding about the gene and the disease.
insulinoma (13 papers, 2011 to 2025). "We showed that 2-DG and/or melatonin affected SOD, catalase, Bcl-2, and Bax proteins in rat insulinoma INS-1E cells, suggesting that 2-DG or 2-DG plus melatonin influences antioxidant and prooxidant proteins through a mechanism involving mitochondrial ROS." (PMID 27493704, 2016). "Next, to characterize intracellular and mitochondrial conditions according to antioxidant and prooxidant proteins, we examined how 2-DG and/or melatonin affected superoxide dismutase (SOD), catalase, Bcl-2, and Bax proteins in rat insulinoma INS-1E cells." (PMID 27493704, 2016). "The results demonstrate that photoactivated hypericin up-regulates cleaved caspases-3, cleaved caspases-9 and Bax-to-Bcl-2 ratio to trigger RINm5F insulinoma cell apoptosis." (PMID 26182357, 2015). "Fragment N is therefore a better beta-cell protector in vivo compared to Bcl-2, which is consistent with in vitro data obtained using the insulinoma cell lines betaTC-tet." (PMID 21799917, 2011). "Similarly, the anti-apoptotic Bcl-2 members, Bcl-2 and Bcl-xL, were reduced by 50–60% in primary rat islets compared to the insulinoma cell line." (PMID 28212395, 2017). "Furthermore, we have found that photoactivated hypericin significantly up-regulates cleaved caspases-9, cleaved caspases-3 and Bax-to-Bcl-2 ratio in RINm5F insulinoma cells." (PMID 26182357, 2015). "Finally, photoactivated hypericin effectively provokes RINm5F insulinoma cell apoptosis through activation of caspase-3 and caspase-9 and elevation of the Bax-to-Bcl-2 ratio." (PMID 26182357, 2015). "To mechanistically understand the photoactivated hypericin-induced apoptosis of RINm5F insulinoma cells, we investigated if photoactivated hypericin impinged on the pro-apoptotic mediators cleaved caspases-3, cleaved caspases-9 and the apoptotic index Bax-to-Bcl-2 ratio by using immunoblot analysis." (PMID 26182357, 2015). "In mouse primary pancreatic islet cells and cultured rat insulinoma INS-1E cells, SA inhibited insulin secretion by stimulating miR-34a-5p to suppress the expression of BCL2 and BCL-W, showing stronger lipotoxic effects than other fatty acids." (PMID 38501107, 2024). "In a rat insulinoma cell line such as the INS-1O, for example, overexpression of AT2R induces caspase-8, caspase-9, and caspase-3 cleavage and decreases Bcl-2, pAkt, and pERK expression levels." (PMID 28599664, 2017). "Western blot analysis indeed revealed a marked but not significant upregulation of Bcl-2 after incubation with Regorafenib in most insulinoma protein lysates compared to DMSO-treated control lysates ex vivo." (PMID 37620408, 2023). "Photoexcited hypericin exerts strong antigrowth activity in RINm5F insulinoma cells via inhibition of cell proliferation by reducing JNK/ERK phosphorylation and stimulation of apoptosis by elevating caspase-9/caspase-3 cleavage and Bax-to-Bcl-2 ratio." (PMID 26182357, 2015). "It was previously reported that Bcl-2 was not significantly influenced by TNF-α and IFN-γ treatment of MIN6 insulinoma cells." (PMID 25811609, 2015).
type 1 diabetes (13 papers, 2009 to 2025). "Compared with women affected by long-term type 1 diabetes only, MAIT cell frequency and survivability (BCL-2+ and CD127+ frequency) were significantly decreased." (PMID 34350463, 2021). "Our data evidenced that STZ-induced type 1 diabetes increased oxidative stress, depressed BAG3, Bcl-2, CaSR and p-eNOS expression and evoked vascular dysfunction in vasoconstriction and vasodilation of the mesenteric arterioles." (PMID 32751309, 2020). "In type 1 diabetes, BH3 mimetics (compounds that mimic the binding of the BH3 to the prosurvival factors in the BCL2 antiapoptotic pathway, such as ABT-199 (also known as venetoclax, targets only BCL2) were effective in NOD mice." (PMID 37822597, 2023). "An example of this situation was reported by Tang and colleagues who observed that intra-islet Treg cells expressed reduced amounts of CD25 and Bcl-2, which led to a functional imbalance of Treg and Teff cell populations leading to the development of type 1 diabetes in non-obese diabetic mice." (PMID 19956753, 2009).
Cirrhosis (12 papers, 2011 to 2025). A chronic disorder of the liver in which liver tissue becomes scarred and is partially replaced by regenerative nodules and fibrotic tissue resulting in loss of liver function. "In contrast, Bcl-2 expression was significantly associated with the presence of cirrhosis (p < 0.0001)." (PMID 21781333, 2011). "Similarly, Bcl-2 expression was significantly associated with poorly-differentiated tumors as well as with the presence of cirrhosis in CH patients." (PMID 21781333, 2011). "Hepatocytes of liver tissues from the cirrhosis rats of Group 2 showed down-regulation of Bax staining with up-regulation of Bcl2-positive hepatocytes and more PCNA staining indicating severe damage with increased number of necrotic cells than their apoptosis." (PMID 23496995, 2013). "Expression of apoptotic genes including Bax and Bcl-2 may vary at different stages of tumor development and progression, such as a hepatic lesion, proliferation/cirrhosis, and carcinogenesis." (PMID 34436030, 2021). "With the mechanistic and phenotypic data generated in the current study, it is possible that blocking BCL2 using Venetoclax might be able to serve as a therapeutic agent for cirrhosis patients with high BCL2 expression." (PMID 32650615, 2020). "This could explain the different profile of Bcl-2 and Bcl-xL expression in the respect to cirrhosis and CH." (PMID 22928777, 2012). "In the current study, we observed significant increase in the serum level of Bax protein and decrease in Bcl-2 protein in silymarin-treated and CLRE- treated animals compared with the cirrhosis group animals." (PMID 23496995, 2013). "Notably, BCL2 expression was upregulated in both HBV- and HCV-infected livers of cirrhosis patients." (PMID 32650615, 2020).
cognitive decline (12 papers, 2020 to 2024). "Overexpression of CaM and CaMKIIɑ blocked the rescue of cognitive decline and neurodegeneration induced by miR-193b-3p and miR-152-3p, respectively, which was associated with activation of the downstream p38/NF-κB and Bcl-2/Bax/caspase-3/PARP pathways." (PMID 37153565, 2023). "Multiple lines of evidence revealed that cadmium-evoked cognitive decline is associated with enhanced hippocampal apoptosis with an increased Bax/Bcl-2 ratio." (PMID 37765022, 2023). "Barbaloin may potentially increase cognitive decline and boost neuronal survival by altering the expression of Bax, caspase-3, Bcl-2." (PMID 38931365, 2024). "Moreover, these pro-inflammatory cytokines induced neuronal apoptosis by enhancing the ratio of Bax and Bcl-2 in N2a cells, providing an explanation for the cognitive decline seen in ICH patients." (PMID 35017318, 2022). "Several studies of streptozotocin-induced diabetic animal model indicated that cognitive decline with downregulation of BDNF and Bcl2 expressions in the hippocampus, BDNF and CREB expressions in the hippocampus, and BDNF and pTrkB levels in the cerebral cortex." (PMID 35743182, 2022).
cyst (12 papers, 2009 to 2025). A sac-like closed membranous structure that may be empty or contain fluid or amorphous material. "In addition, BCl-2 and Ki-67 proteins, which are predictive indicators closely associated with cell proliferation, were analyzed in cyst fluids." (PMID 35538039, 2022). "Immunohistochemical analysis has revealed the presence of amelogenin within ghost cells, along with the expression of CK19, Bcl-2, and Ki-67 in the cyst epithelium." (PMID 39811793, 2025). "In this study, higher expression levels of BCL-2 and Ki-67 were found in the bacteria-positive cyst fluids, consistent with previous reports." (PMID 35538039, 2022). "This was supported by an induction of caspase-3 and gadd45a expression in the cyst and a downregulation of BCL-2 and BAX in the adjacent lung tissues." (PMID 35274045, 2021). "To note, bcl2 staining of control lymphocytes was weak after decalcification of case K19 compared to the biopsy sample of the same cyst and samples of other cysts." (PMID 32632899, 2020). "In vitro, similar phenomena have been observed in MCF-10A epithelial cell cultures: cells accumulated inside cyst lumens when an anti-apoptotic protein, Bcl-2 was overexpressed." (PMID 20043854, 2009). "According to our results,Pseudomonas exacerbates the pathogenesis by increasing the productions of TNF-α, IL-1α, BCL-2 and Ki-67, suggesting that this facultative anaerobic bacterium may trigger the pathogenesis of cyst formation." (PMID 35538039, 2022). "In addition, the protein levels of BCL-2 and Ki-67 were the highest inPseudomonas positive cyst fluids." (PMID 35538039, 2022). "On this basis, we speculated that 45 Gy might be a safe and effective dose for treating pulmonary hydatidosis in sheep, which induced lower expression of caspase-3 and gadd45a in the cyst and a downregulation of BCL-2 and BAX in the adjacent lung tissues." (PMID 35274045, 2021). "However, a dose of 45 Gy significantly suppressed the expression of BCL-2 and BAX in the lung tissues involved by the cyst, suggesting beneficial effects on the host." (PMID 35274045, 2021). "Of these, the developmental cysts without inflammation demonstrated some (faint to moderate) basal bcl2 staining, without suprabasal extension, and all of the rarer cyst types also displayed various CK17 expression, including focal transepithelial staining." (PMID 32632899, 2020). "Basal bcl2 labelling was not common in non-OKCs, but was also seen in some other cyst types, most commonly in dentigerous cysts." (PMID 32632899, 2020). "In the CXB treatment group, the ratio of Bcl-2/Bax and the amount of phospho-ERK1/2 were decreased in time-dependent manners, suggesting that CXB might increased the sensitivity of ADPKD cyst-lining epithelial cells to apoptotic stimuli." (PMID 22415852, 2012). "The only cyst (K2) where the IHC helped to make the diagnosis of OKC was an inflamed OKC with a small bit of transitional epithelium with basal bcl2 and patchy transepithelial (non-typical) CK17 staining and minimal typical residual epithelium identified only on revision and recut." (PMID 32632899, 2020). "Although the characteristic CK17 and bcl2 IHCs are rare in combination in non-OKCs, inflamed OKCs also loose these stains at the sites of altered epithelium, which may form the majority or the whole of the cyst lining." (PMID 32632899, 2020).
emphysema (12 papers, 2010 to 2025). "The depletion of DNMT1 by shRNA or inhibition of DNMT1 with AZA markedly reduced lung function damage, emphysema, pulmonary apoptosis, and Bcl-2 expression, suggesting that CS exposure causes emphysema, pulmonary apoptosis and hypermethylation through DNMT1." (PMID 32883320, 2020). "For example, DNMT1 contributed to hypermethylation of the Bcl‐2 promoter, which diminished the protein expression of Bcl‐2, thereby impairing lung function in a mouse model of emphysema." (PMID 35678255, 2022). "Our results showed that HOTAIR mRNA levels were significantly up-regulated in the HPVEC of patients with COPD, and HOTAIR down-expression can attenuate CSE-induced cell apoptosis and emphysema via DNMT1 mediated hypermethylation of Bcl-2 promoter in mice." (PMID 36527094, 2022). "Knockdown HOTAIR can attenuate cell apoptosis and emphysema via DNMT1 mediated hypermethylation of Bcl-2 promoter in mice." (PMID 36527094, 2022). "Bcl-2 promoter methylation lowers Bcl-2 expression, which leads to apoptosis of cells in the alveolar walls and generates premature emphysema [27••]." (PMID 34735706, 2021). "Cigarette-induced oxidative stress mediates pulmonary apoptosis and hypermethylation of the Bcl-2 promoter in emphysema models through DNMT1." (PMID 32883320, 2020). "Following DNMT1 blockade, smoking models showed improved lung function, pulmonary apoptosis, emphysematous progression, and increased Bcl-2 protein level with less promoter methylation than emphysema mice." (PMID 32883320, 2020). "Also, the expression of cleaved caspase-3 was increased and anti-apoptotic protein Bcl2 was decreased in emphysema mice." (PMID 37822364, 2023). "Furthermore, rat models of pulmonary emphysema demonstrated that MSCs reduce AEC apoptosis through paracrine mechanism via up-regulation of anti-apoptotic Bcl-2 gene." (PMID 23350749, 2013). "Because of the elevated HOTAIR mRNA level and hypermethylation of Bcl-2 in the lung tissue of emphysema subjects, we tested whether modulation of the HOTAIR mRNA level or activity ameliorates emphysema, pulmonary apoptosis and Bcl-2 promoter hypermethylation in mouse models." (PMID 36527094, 2022). "Because of the elevated DNMT1 protein level and hypermethylation of Bcl-2 in the lung tissue of emphysema subjects, we tested whether modulation of the DNMT1 protein level or activity ameliorates emphysema, pulmonary apoptosis and Bcl-2 promoter hypermethylation in mouse models." (PMID 32883320, 2020). "The expression of DNMT1 in the lung tissue of COPD patients increased and DNMT1 can mediate the hypermethylation of the Bcl-2 promoter, thus enhancing apoptosis in the lung tissue of CSE induced emphysema mice." (PMID 37822364, 2023). "Further, in a mouse model of emphysema, DNMT1 has been highlighted to induce hypermethylation of the Bcl‐2 promoter and downregulate Bcl‐2, which is an anti‐apoptotic factor to repress cell apoptosis." (PMID 35678255, 2022). "Because of the activation of NF-κB, an increased level of Bax and downregulation of Nrf2 and Bcl-2 have been reported in the lung tissue of emphysema patients, thus, OMT has the great potential to alleviate emphysema via modulating these signaling pathways." (PMID 35684546, 2022). "HPVEC apoptosis with down-regulated Bcl-2 expression, increased promoter methylation, DNMT1, Bax and Cleaved-caspase 3 expression was found in emphysema mouse model and CSE-induced HPVEC." (PMID 36527094, 2022). "HOTAIR knockdown mice presented increased levels of Bcl-2 and decreased levels of Bax and Cleaved-caspase 3 in the lungs, which indicates that HOTAIR gene silencing prevented emphysema and pulmonary apoptosis in CS exposed mice." (PMID 36527094, 2022). "We also demonstrated that Bcl-2 protein level was decreased in emphysema models and COPD patients, suggesting that Bcl-2 is involved in COPD pathogenesis." (PMID 32883320, 2020).
emphysema (continued). "Our previous studies found a high methylation status of the whole genome and hypermethylation of the Bcl-2 promoter in COPD patients and emphysema models, and demethylation treatment could protect models from emphysema." (PMID 32883320, 2020). "Almost all non-COPD smokers in our study did not experience emphysema, suggesting that Bcl-2 might specifically be involved in emphysema rather than other pathogenic processes of COPD." (PMID 32883320, 2020).
endothelial dysfunction (12 papers, 2015 to 2026). In vascular diseases, endothelial dysfunction is a systemic pathological state of the endothelium (the inner lining of blood vessels) and can be broadly defined as an imbalance between vasodilating and vasoconstricting substances produced by (or acting on) the endothelium. "In particular, we assessed the mitochondrial homeostasis markers like expression of the anti-apoptotic protein Bcl-2 level and mitochondrial oxidative stress, as well as markers of endothelial dysfunction." (PMID 39616228, 2024). "Furthermore, the expression of Bcl2, a key regulator of apoptosis, and Vwf, a marker of endothelial dysfunction, was higher in DTG mice." (PMID 33995116, 2021). "TAS attenuated endothelial dysfunction through the activation of PI3K/Akt signalling, followed by regulating the levels of inflammatory factors and the expression of Bcl-2 family proteins, such as Bax and Bcl-2, which led to decreased levels of activated caspase-3." (PMID 30577658, 2018).
HIV-1 infection (12 papers, 2006 to 2025). The type species of lentivirus and the etiologic agent of acquired immunodeficiency syndrome (AIDS). "High levels of caspase-1 and caspase-3, and low levels of Bcl-2 in platelet-CD4+ T cell aggregates imply the potential role in CD4+ T cell loss during HIV-1 infection." (PMID 34987521, 2021). "In the context of latent HIV-1 infection, expression of anti-apoptotic proteins, e.g. Bcl-2, is elevated whereas pro-apoptotic proteins are inhibited favoring cell survival of latently infected cells." (PMID 37558852, 2024). "BCL-2 is upregulated in HIV-1 infection due to an increase in phosphorylated STAT5 that promotes transcription of the BCL-2 gene." (PMID 34790202, 2021). "Based on these interesting findings, it will be necessary to focus specifically on the transcriptional factors (NF-κB and SP1) and pro-apoptotic genes (bcl-2) in future research on bDLE as an antiviral against HIV-1 infection." (PMID 22044844, 2011). "Of note, in NK cells from patients with HIV-1 infection, mRNA expression of Bcl-2 and Bcl-xL was consistently lower than that of healthy donors; interestingly, TGF-β and Tat were detected in the sera of these patients." (PMID 17162379, 2006).